IL5 (interleukin 5)
Diseases named in the same sentence as IL5 in open-access papers (continued):
Sharing a sentence is not in itself a finding about the gene and the disease.
melanoma (21 papers, 2010 to 2025). A malignant, usually aggressive tumor composed of atypical, neoplastic melanocytes. "An association between IL-5 and eosinophils was observed in melanoma where IL-5 administration was related to enhanced eosinophils infiltration and anti-metastatic activity in the lung." (PMID 36376448, 2023). "In HCC, similar to observations in melanoma, CCL11-expressing tumors demonstrate that IL-5/CCL11 co-stimulation effectively recruits tumor-associated eosinophils, potentially mediating both immune evasion and tumoricidal effects." (PMID 40429807, 2025). "In 2012, Ikutani and coworkers reported that, in a mouse model of melanoma lung metastasis, ILC2s responded to melanoma cells by secreting IL-5, which in turn promoted eosinophil recruitment and activation, thus counteracting metastasization." (PMID 36765891, 2023). "In another melanoma model, IL-33 induced proliferation of innate IL-5-producing non-T cells upon tumor invasion, and the regulation of eosinophils by these IL-5-producing cells appeared to be critical to limit tumor metastasis." (PMID 34209038, 2021). "In mice, ILC2s have been found to maintain sufficient numbers of eosinophils in the lungs through the production of IL-5 in response to melanoma invasion." (PMID 34691082, 2021). "Based on these findings, the prognosis of melanoma may be improved by reducing the IL-5 levels through improving QOL via sufficient physical and emotional support." (PMID 36405903, 2022). "Additionally, genetic blockade or antibody-mediated neutralization of IL-5 has been shown to impair eosinophil recruitment into the lungs leading to an increased metastatic dissemination of melanoma cells." (PMID 34691082, 2021). "Interestingly, the Th2 cytokine IL-5 was significantly increased in the plasma of NAM-treated melanoma-bearing mice, while IL-12 (p40), a typical Th1 cytokine, was decreased, indicating a shift toward a Th2 profile in NAM-treated melanoma-bearing mice." (PMID 33028392, 2020). "Further, analysis of clusters identified within the melanoma patient set comparing patient outcome suggests that suppression of IL-1α, IL-4, IL-5, and CCL22, with concomitant elevation of CXCL10, CCL4, and CCL17, may correlate with more aggressive development of brain metastasis." (PMID 36527157, 2022). "In response to autologous melanoma cell line, this clone is lytic and produced in decreasing order the following Th1 and Th2 cytokines: IL-13, IL-4, TNF-α, GM-CSF, IL-2, IFN-γ and IL-5." (PMID 20052413, 2010). "Although the relationship between melanoma and IL-5 has not been studied, IL-5 facilitates lung metastasis by modulating the immune environment." (PMID 36405903, 2022). "A study of individual CSF samples from 22 patients with melanoma brain metastases and 5 disease-free controls found that Chemokine CCL22 and cytokines IL-1α, IL-4, and IL-5 were reduced in most samples, whereas a subset of molecules including CXCL10, CCL4, CCL17, and IL8 increased expression." (PMID 36527157, 2022). "Furthermore, IL-33 EO, unlike IL-5 EO, interfered with tumor 3D-spheroid formation in vitro and slowed tumor outgrowth in vivo when co-injected with B16 melanoma cells into syngeneic mice." (PMID 31717819, 2019). "Though Nivolumab did not significantly alter serum cytokine profiles, in melanoma patients we observed a deviation from the physiological range for 7 out 18 cytokines tested: IL-1β, IL-6, CCL2, CXCL8, VEGF, IL-5 and IL-13." (PMID 35173725, 2022). "We also evaluated the protein amount of a set of 12 cytokines and chemokines, including IL-2, IL-4, IL-5, IL-6, IL-10, IL-12, IL-17A, TNF-α, IFN-γ, MCP-1, MIP-1α, and eotaxin in TIF and plasma samples of C57BL6 mice, engrafted or not engrafted with B16 melanoma cells." (PMID 34604232, 2021).
melanoma (continued). "Notably, type 2 cytokine responses (IL-5) and neutrophil responses (CXCL8/IL-8) were not altered by the changes of CD40 expression, suggesting that CD40 expression specifically correlates to the T-cell-dependent antitumor immunity in human melanoma tumors." (PMID 34092233, 2021).
Granuloma (19 papers, 2006 to 2025). A compact, organized collection of mature mononuclear phagocytes, which may be but is not necessarily accompanied by accessory features such as necrosis. "In murine histoplasmosis infection, increased levels of IL-5 have been associated with Histoplasma-induced granulomas in the liver and the lung." (PMID 34829225, 2021). "Studies have shown that the blockage of this cytokine by neutralizing antibodies results in a reduction of the granuloma area associated with a decrease in IL-5 secretion by T cells." (PMID 31886307, 2019). "Moreover, infected KO rats displayed a marked decrease in the levels of both Th1- (IFN-γ) and Th2-associated cytokines (IL-4, IL-5) at all time points post-infection, except with IL-2 and IL-13, both of which play an important role in granuloma and fibrosis development." (PMID 35584107, 2022). "Cytokines such as IL-1β, IL-4 IL-5, IL-6, IL-13, TNF-α, MCP-1, and TSLP induce allergy-related inflammation, which causes tissue fibrosis, granuloma formation, and leukocyte infiltration." (PMID 36235405, 2022). "Studies in vitro showed that myofibroblasts release CCL11 and IL-5, crucial molecules for the recruitment and accumulation of eosinophils in granulomas." (PMID 36296298, 2022). "Most experimental studies demonstrate the role of Th2 cytokines (IL-4, IL-5, and IL-13) in the formation of granuloma and of the Th17 response in advanced fibrosis." (PMID 34970264, 2021). "Type-2 cytokines, such as IL-5, IL-4, and IL-13, are responsible for the recruitment and activation of immune cells involved in granuloma formation, whereas IL-10 has been related to the granuloma modulation." (PMID 31886307, 2019). "Classically, the granuloma evolution is related to a Th2 cytokine profile (i.e., IL-4, IL-5, and IL-13) and lower IFN-γ expression." (PMID 31019973, 2019). "Using a commercial kit to detect typical Th1/Th2 cytokines, we compared the levels of IFN-γ, TNF-α, IL-2, IL-4, and IL-5 in lung homogenates 14 days after granuloma induction and in serum samples collected 1, 5, 14 and 18 days after granuloma induction." (PMID 22013486, 2012). "As expected, the granulomas in the IL-5−/− mice were nearly devoid of eosinophils at both time points (<1.0% of all cells), while the granulomas in the WT mice were composed of approximately 50% eosinophils." (PMID 19381262, 2009). "A low level of IL-5 mRNA expression was detectable in all granulomas as was the level of IL-2 expression." (PMID 16542426, 2006). "Notably, mice that did present with granulomas appeared to have changes to lymphoid follicles and enhanced humoral responses, indicated by increased IL-4, IL-5, and IL-10 in splenocyte supernatants." (PMID 40375983, 2025). "One previous study has quantified mRNA levels of IL-4 in sarcoidosis and tuberculosis granulomas within diseased lymph nodes and found that four out of eight tuberculosis samples expressed detectable amounts of IL-4 and/or IL-5 mRNA, compared with undetectable levels in six sarcoidosis samples." (PMID 22815689, 2012). "At 119 dpi an increased number of granuloma was observed in the IL-4R−/−/IL-5−/− mice, which hampered the exact worm counts and may explain the lower worm numbers in comparison to the dblGATA and IL-5−/− mice." (PMID 31109364, 2019). "The release of IL-5 by CD4+ T lymphocytes, a key cytokine involved in the development and activation of eosinophils, leads to eosinophil recruitment to tissue sites in which granulomas are in the process of formation around parasite eggs." (PMID 36296298, 2022). "Previous studies have shown that the deficiency of B cell or B-1a cell has led to a higher mortality in schistosome-infected mice, as well as that B-1a cells regulate the IL-5 and IFN-γ production of Th cells and control the size of ova granulomas during infection." (PMID 32197642, 2020).
Granuloma (continued). "In addition, the profile of IL-5 mRNA expression, which differs from that of IFN-γ, suggests that these two cytokines play different roles in the formation of granulomas." (PMID 16542426, 2006).
rhinitis (19 papers, 2010 to 2024). An inflammation of the mucous membrane lining the nose, usually associated with nasal discharge. "IL-10 is also associated with IL-5 in urticaria as well as those showing skin and rhinitis." (PMID 20616938, 2010). "Nasal biopsies of rhinitis patients showed increased IL-4, IL-5, IL-13 mRNA expression suggesting a Th2 cytokine profile." (PMID 24116013, 2013). "Moreover, ARNO-/- mice showed a reduced eosinophilic inflammation and IL-5 expression in an OVA-induced model of rhinitis." (PMID 35095899, 2021). "Hairdressers with rhinitis to bleach showed increases in apolipoprotein A1, IL-5, IFN-Y in post SIC nasal lavage, while, in atopics, an increase in IL-5 and IL-13 was found." (PMID 35316371, 2022). "Additionally, rhinitis was absent in any post-marketing documentation of anti-IL-5 pharmaceuticals." (PMID 38308249, 2024).
chronic asthma (18 papers, 2013 to 2025). An asthma that is characterized by the development of persistent airway inflammation and recurrent attacks of breathlessness and wheezing, which vary in severity and frequency. "In contrast, in the chronic asthma model, each of the Th2 cytokine transcripts was modestly reduced in the sPLA2-deficient mice (i.e., reductions of 22% for IL-4, 19% for IL-5, an 49% for IL-13)." (PMID 23451035, 2013). "In the chronic asthma model, the extended exposure to such allergens as ovalbumin and fungal extracts led to significantly elevated levels of IL-5 and TGF-β compared to the acute asthma model." (PMID 40558541, 2025). "One exception was IL-5 in the context of chronic asthma challenged by P. ficariae, where the cream titer slightly exceeded the level observed after using OVA." (PMID 40558541, 2025). "Due to the narrow cellular targets of IL-5 and the key role it plays in all areas of eosinophil biology, IL-5 represents a unique area for therapeutic intervention to alleviate chronic asthma." (PMID 36232470, 2022). "Consistent with the roles of CD146 in the inflammatory response, IL-4, IL-5, IL-1, and IFN-γ levels were significantly reduced in CD146-deficient mice with chronic asthma." (PMID 32793232, 2020). "This study aimed to evaluate plasma CCL5 (chemokine) and IL-5 (cytokine) as well as eosinophils in peripheral blood and sputum and their possible role in patients with chronic asthma who visited emergency rooms during sandstorms." (PMID 32467785, 2020). "Curcumin administered intranasally prevented remodeling related to chronic asthma, structural alterations, airway inflammatory cell accumulation, and mucus secretion in the OVA-induced murine model of chronic asthma, along with a decrease in IL-5, IL-4, and IgE levels." (PMID 39263346, 2024). "In addition, our results demonstrated an increase in the levels of the main pro-inflammatory cytokines found in chronic asthma (IL-4, IL-5, and IL-13) and reduced the anti-inflammatory IL-10." (PMID 35185864, 2021). "However, the levels of IL-4, IL-5, and IL-13 substantially decreased in mice with chronic asthma compared with those in mice with acute asthma." (PMID 34671356, 2021). "However, treatment directed at TRPV1 significantly alleviated IL-4, IL-5, and IL-13 level in a chronic asthma murine model, while conversely TRPA1 promoted OVA-induced IL-4 production during acute allergic lung inflammation." (PMID 34099759, 2021). "This study aimed to evaluate the usefulness of C-C chemokine ligand 5 (CCL5) chemokine and interleukin 5 (IL-5) cytokine and determine the total eosinophil count in blood and sputum for use as biomarkers in Saudi patients with chronic asthma who visited emergency departments during sandstorms." (PMID 32467785, 2020). "In mice chronic asthma models tiotropium significantly decreased smooth muscle thickening and peribronchial collagen deposition, with a parallel reduction of Th2-mediated cytokines such as IL5 and IL13." (PMID 29213218, 2017). "Both fungal extracts significantly elevated the IL-4, IL-5, IL-13, TNF-α, and TGF-β levels in mice with acute and chronic asthma." (PMID 40558541, 2025). "Inflammatory cytokines in lung homogenate, such as IL-4, IL-5, and IFN-γ, were significantly increased in the chronic asthma model." (PMID 37432745, 2023). "HE staining and ELISA detection results of inflammatory factors (IL-4, IL-5, and IL-13) showed that the inflammatory response was substantially higher in OVA-induced acute asthma (OVA-4 weeks group) than that in chronic asthma (OVA-8 weeks group)." (PMID 34671356, 2021). "In 2012, due to the known side effects of long term oral steroid use, the GINA guidelines downgraded the use of oral CS in chronic asthma and recommend them only if other controllers, such as anti-IgE and anti-IL-5, were not available or did not work." (PMID 33076829, 2020).
co-infection (18 papers, 2009 to 2025). "Co-infection with HTLV-1 reduces interleukin-5 and immunoglobulin E responses and switches from Th2 to Th1 responses in patients with strongyloidiasis." (PMID 40768511, 2025). "The authors showed that co-infection of mice with M. sympodialis and S. aureus or p. aeruginosa increased allergic and inflammatory responses by significantly increasing the level of IL-5, IL-13 and IL-17, respectively." (PMID 34682276, 2021). "In patients with HTLV-1 and S. stercoralis co-infection, regulatory T-cell counts are increased and correlate with both low circulating eosinophil counts and reduced antigen-driven IL-5 production." (PMID 28464844, 2017). "This is in line with previous reports, including reduced schistosome-specific IL-4 and IL-5 in Plasmodium and schistosome co-infected individuals and suppressed IL-4 responses during H. polygyrus and Plasmodium yeolii co-infection." (PMID 26147567, 2015). "During human co-infection with S. stercoralis and HTLV-1, increased production of interferon-γ (IFN-γ) and interleukin-10 (IL-10) is associated with decreased production of interleukin 5 (IL-5) by peripheral blood mononuclear cells (PBMCs)." (PMID 25499310, 2014). "Regulatory T cell counts are increased in patients with HTLV-1 and Strongyloides stercoralis co-infection and correlate with both low circulating eosinophil counts and reduced antigen-driven IL-5 production." (PMID 19513105, 2009). "IL-5- was elevated in the helminth and coinfection group versus the control group." (PMID 37513018, 2023). "By contrast, patients with S. stercoralis and HTLV-1 co-infection have reduced IL-5 responses to parasite antigens, which may lead to decreased eosinophil count." (PMID 19513105, 2009). "Compared with P. berghei ANKA-mono-infection group, the co-infection group showed a significantly lower level of IFN-γ on day 5 and day 8 pi and significantly higher levels of IL-4, IL-5 and IL-13 on day 3, 5, 8 pi." (PMID 24034228, 2013). "Using our modelling approach we showed that IL5 and IL13 had complementary abilities against helminths and contributed to parasite reduction both in single and co-infection." (PMID 22253585, 2012). "Co-infection group and HIV mono-infection group revealed a slightly elevation of IL-5 concentration when compared with HCV mono-infection and healthy control group (p > 0.05), while the same level between HIV mono-infection." (PMID 22533731, 2012). "Previous studies have demonstrated lower eosinophil counts, decreased production of IL-5, and increased production of interferon gamma in patients with S. stercoralis and HTLV-1 co-infection." (PMID 19513105, 2009). "Compared to P. berghei-mono, mice in the co-infection-100c group had significantly lower levels of IFN-γ on days 5 and 8 pi and higher levels of IL-4, IL-5, IL-13 and TGF-β on days 3, 5, and 8 pi, while no significant changes in IL-10 levels were observed between the two groups." (PMID 24670210, 2014).
eosinophilic esophagitis (18 papers, 2014 to 2025). Eosinophilic esophagitis (EoE) is a chronic, allergic disease of the esophagus characterized clinically by symptoms of esophageal dysfunction (including vomiting, dysphagia, feeding disorders, food impaction and abdominal pain) which persist after treatment with proton pump inhibitors (PPIs). "Eosinophilic esophagitis (EoE) is a chronic, Th2-associated inflammatory disorder characterized by pronounced inflammation of the esophagus with cytokines such as Il-5, Il-13, Il-4, and IgE that contribute significantly to the EoE pathogenesis, similarly to AD." (PMID 38256267, 2024). "Other pathogenic mechanisms may be involved in the progression of eosinophilic esophagitis beyond IL-5-driven eosinophilia." (PMID 37764213, 2023). "The anti-IL-5 antibodies, mepolizumab and reslizumab, bind to IL-5 and are also able to mitigate eosinophilic esophagitis through the prevention of IL-5 signaling, reducing the production and survival of eosinophils." (PMID 40004029, 2025). "Benralizumab demonstrates strong efficacy in treating severe eosinophilic asthma and eosinophilic esophagitis (EoE), conditions in which disease pathology is largely driven by an overabundance of eosinophils and their activation via the IL‐5 pathway." (PMID 40781582, 2025). "Mepolizumab and reslizumab, anti-IL5 antibodies approved for the treatment of eosinophilic asthma, have been investigated for the treatment of eosinophilic esophagitis." (PMID 37764213, 2023). "The anti–interleukin-5 antibody mepolizumab is useful for treating bronchial asthma and eosinophilic polyangiitis granulomatosa, and its efficacy in eosinophilic esophagitis has also been investigated." (PMID 39132061, 2022). "The anti–IL-5 antibody mepolizumab has been shown to be clinically and histologically effective in the treatment of eosinophilic esophagitis." (PMID 39132061, 2022). "It has been previously shown that IL-5 could induce eosinophilic esophagitis in animal models, and the administration of anti-IL-5 antibodies seems to block this process." (PMID 36140492, 2022). "Finally, as there are similarities in the pathogenesis of EC with eosinophilic esophagitis (EoE), biologic medications undergoing clinical trials for the treatment of EoE are potential therapeutic agents for EC (Anti-IL5, anti-IgE monoclonal antibodies, anti-tumor necrosis factor (TNF-α)." (PMID 38238810, 2024). "Interleukin-5 (IL-5) has recently been shown to play a crucial role in eosinophil-mediated diseases, implying that an IL-5 receptor alpha chain (IL-5Rα) antibody (benralizumab) can be effective against eosinophilic esophagitis (EoE)." (PMID 38267847, 2024). "The IL-5-targeting agents mepolizumab and reslizumab, commonly prescribed for severe eosinophilic asthma, showed histologic improvements in eosinophilic esophagitis (e.g., reduction in eosinophils), but failed to induce symptomatic improvement." (PMID 37138643, 2023).